TFPI (tissue factor pathway inhibitor)
Diseases named in the same sentence as TFPI in open-access papers (continued):
Sharing a sentence is not in itself a finding about the gene and the disease.
tumor (continued). "This molecule's Kunitz-type domain is similar to that of the endogenous tissue factor pathway inhibitor (TFPI) and can reduce tumor growth and metastasis in vivo." (PMID 25479096, 2014). "It has been suggested that the effects of heparin and related molecules in models of tumour growth and metastasis rely, at least in part, on the promotion of tissue factor pathway inhibitor (TFPI) release from endothelial cells." (PMID 23984092, 2013). "Using an experimental metastasis mouse model, Amirkhosravi and colleagues found that the intravenous injection of recombinant mouse tissue factor pathway inhibitor (TFPI) immediately before inoculation of tumor cells reduced metastasis by 83%." (PMID 22837985, 2012). "Several cancer tissues and cell lines have been shown to express TFPI, and TFPI treatment has been reported to reduce tumor growth and metastasis in vivo." (PMID 23071754, 2012). "TF has been shown to promote tumor cell migration, invasion, growth, and metastasis, and Hembrough and colleagues reported that TFPI suppressed metastatic tumor growth in vivo through inhibition of TF/FVIIa activity." (PMID 21849050, 2011). "The effects of TFPI, a “tumor suppressor-like molecule,” include enhanced apoptosis and blocked tumor growth and angiogenesis." (PMID 21941675, 2011). "Produced by ECs and tumor cells, most TFPI is expressed on the cell surface, although it can be detected peripherally in plasma." (PMID 15969748, 2005). "Our earlier studies demonstrated that heparanase up-regulates the expression of TF and interacts with the tissue factor pathway inhibitor (TFPI) on the cell surface membrane of endothelial and tumor cells, ensuing by TFPI dissociation and enhanced cell surface coagulation activity." (PMID 39859197, 2025). "Prior studies have demonstrated that TFPI inhibits proliferation only at excessive concentrations through an apoptotic mechanism and may indirectly affect tumor growth at lower concentrations by inhibiting angiogenesis through a nonhemostatic mechanism." (PMID 38360687, 2024). "Our findings align with emerging evidence suggesting TFPI might actively contribute to tumor progression." (PMID 38576019, 2024). "It is of interest that in experimental melanoma, TFPI-1 and -2 inhibit vasculogenic mimicry (VM), during which aggressive tumor cells form vessel-like networks without typical ECs to supply sufficient blood to the growing tumor." (PMID 39153052, 2024). "By interfering with CD147, TFPI may disrupt key signaling pathways involved in tumor migration and metastasis." (PMID 38360687, 2024). "Our earlier studies showed that heparanase up-regulated the expression of TF and interacted with the tissue factor pathway inhibitor (TFPI) on the cell surface membrane of endothelial and tumor cells, resulting in TFPI dissociation and increased cell surface coagulation activity." (PMID 39766213, 2024). "Various studies have suggested that therapeutic strategies that target an increase in the expression of TFPI could inhibit tumor angiogenesis, growth, and metastasis." (PMID 39149564, 2024). "The impact of combining TFPI or its inducers LMWHs with a CD147 inhibitor could be influenced by the specific tumor microenvironment in vivo." (PMID 38360687, 2024). "Increased HPA regulates the expression of coagulation factor TF13 and interacts with TFPI (tissue factor pathway inhibitor) on the cell membrane surface of endothelial cells and tumor cells, resulting in the dissociation of TFPI, thereby increasing the coagulation activity on the cell surface." (PMID 37361227, 2023). "Based on success studies of coagulation factor inhibitors from hematophagous organisms in tumor cell lines and due to Amblyomin-X’s similarity with TFPI, a viability assay was performed with several tumor cell lines to evaluate the antitumor activity of this molecule." (PMID 36052162, 2022).
tumor (continued). "In addition to its cytotoxic activity, Amblyomin-X can regulate cell adhesion and migration of human tumor cells like TFPI and TFPI-2." (PMID 36052162, 2022). "On the contrary, the TFPI-2, originally identified by TFPI-1 homology as placental trypsin and serine protease inhibitor associated with tumour cell ECM, does not physiologically exert any inhibitory activity on the TF pathway." (PMID 36224457, 2022). "Namely, TFPI is involved in inhibiting the pro-coagulatory activity of TF, but it does not balance the activity of TF, while TFPI-2 seems to be a factor regulating the processes of tumor growth and progression." (PMID 33947134, 2021). "This may suggest a modeling effect of TFPI on TF-dependent signaling functions and thus on tumor growth and progression." (PMID 33947134, 2021). "Moreover, HPSE interacts with the tissue factor pathway inhibitor (TFPI) on the cell surface of endothelial and tumor cells, leading to dissociation of TFPI and causing increased cell surface coagulation activity." (PMID 30487472, 2018). "Through the interactions, TFPI-1 may be partly involved in tumor metastasis and consumed, and lower TFPI-1 was consistent with these processes." (PMID 28246607, 2017). "Logistic regression analyses showed that TFPI-1 was the independent risk factor related to DVT and tumor metastasis in NSCLC patients (odds ratio, 3.651; 95% confidence interval, 3.011~4.378, P = 0.00; odds ratio, 3.122; 95% confidence interval, 2.620~3.781, P = 0.00, resp)." (PMID 28246607, 2017). "And lower TFPI-1 levels in patients with metastasis may be explained by what TF-VIIa/TFPI-1 interactions which can promote tumor cell adhesion and migration." (PMID 28246607, 2017). "In NSCLC patients with DVT or metastasis, lower TFPI-1 level may be due to consumption by tissue factor from tumor cells or damaged endothelial cells in ongoing coagulation activation." (PMID 28246607, 2017). "Together with the previously demonstrated tumor suppressor effects of TFPI, the beneficial survival effect of tumor-expressed TFPI highlights the potential of TFPI as a candidate in cancer therapy, and this clearly deserves further investigation for possible translation to clinical practice." (PMID 25882602, 2015). "Based on our results, we hypothesize that TFPI could be a novel ligand mediating the arrest of TF-expressing tumor cells in high TFPI-expressing vessels under conditions of low shear during metastasis." (PMID 25849335, 2015). "Together with the previously demonstrated tumor suppressor effects of TFPI, the beneficial effect of tumor expressed TFPI on survival, renders TFPI as a potential anticancer agent, and the clinical significance of TFPI in cancer deserves further investigation." (PMID 25882602, 2015). "This covariate-adjusted analysis showed that low total TFPI (α + β) expression was a prognostic indicator for overall survival, independent of the strong association with tumor size." (PMID 25882602, 2015). "The microfluidic system used herein to study tumor cell adhesion is a simple system of straight channels and immobilized recombinant proteins, but it was sufficient to show that high TF-expressing tumor cells can bind to high concentrations of immobilized recombinant TFPI under low shear." (PMID 25849335, 2015). "Based on our results, we hypothesize that endothelial cells with high constitutive TFPI expression could potentially arrest high TF-expressing tumor cells through adhesive interactions under low shear in vivo." (PMID 25849335, 2015). "Our results support our current hypothesis that TFPI, which is constitutively expressed on the endothelium, can be another candidate responsible for helping the capture of high TF-expressing tumor cells to endothelial cells with high TFPI expression." (PMID 25849335, 2015). "Taken together, we hypothesize that TFPI is a marker of more aggressive tumors while at the same time being a tumor suppressor." (PMID 25882602, 2015).
tumor (continued). "Hence, we first tested adhesion of high and low TF-expressing tumor cells to TFPI under low shear (0.35dyn/cm2)." (PMID 25849335, 2015). "We hypothesized that TF-expressing tumor cells can bind to immobilized recombinant TFPI, leading to arrest of the tumor cells under shear in vitro." (PMID 25849335, 2015). "The hemostatic function of heparanase, executed by inducing TF expression and releasing TFPI from the endothelial cell surface, provides a mechanism by which heparanase contributes to tumor complication, in addition to its established proangiogenic and prometastatic activities." (PMID 23908827, 2012). "This indicates a possibly therapeutic potential of TFPI that could affect tumor grade and perhaps patient outcome." (PMID 23071754, 2012). "In tumor cells, the diminished expression of TFPI could result in activated factor Xa and increase factor Xa-PAR-2 signaling." (PMID 15969748, 2005). "Results from in vitro and in vivo studies have suggested that therapeutic strategies that target an increase in the expression of TFPI could inhibit tumor angiogenesis, growth, and metastasis." (PMID 15969748, 2005). "TFPI-1 was observed to serve as the predominant regulator of TF activity in aggressive melanoma cells (behaving thus as endothelial cells), and its anticoagulant activity could account for the fluid-conducting capacity of VM tumour cell-lined vessels." (PMID 36224457, 2022). "In addition, another method was found by Gamperl in 2016, which was a low-molecular weight heparin called Tinzaparin that can induce the release of the tissue factor pathway inhibitor (TFPI) from tumor cells, and the recombinant TFPI then inhibits the TEXs inducing tumor cell migration." (PMID 33922480, 2021). "We speculate that TFPI presents dualistic functions and from one side might be an indicator of tumour expansion and invasive behaviour as well as simultaneously presenting antiproliferative properties and being tumour suppressant." (PMID 29475895, 2018). "Therefore, the association between TFPI-1 and NSCLC may provide a possible explanation for NSCLC being closely related to DVT, even tumor metastasis." (PMID 28246607, 2017). "Therefore, NSCLC patients with decreased TFPI-1 levels may be in risk for DVT and tumor metastasis, which indicates that TFPI-1 is useful to predict DVT and tumor metastasis at the time of diagnosis of NSCLC." (PMID 28246607, 2017). "TFPI expression in tumors may then serve to oppose and protect against tumor progression." (PMID 25882602, 2015). "However, it remains to clarify whether the GPI-attached TFPI is indeed able to inhibit TF signaling, which is important in the pro-tumor effect of TF, or if the effects are due to signaling mechanisms independent of TF." (PMID 23320987, 2013). "It had already been reported that TFPI-2 had an anti-invasive effect that might be mediated via inhibition of plasmin that activates proteases promoting degradation of extracellular matrix and tumor invasion." (PMID 18053161, 2007). "Its understanding becomes more challenging when taking into account that TFPI was shown to bind ECM components, thus supporting the TF/FVIIa complex to promote tumor cell adhesion and migration." (PMID 36900315, 2023). "In accordance with these potentially tumor-promoting properties of TF, its natural inhibitors TFPI-1 and TFPI-2 have been described to act as tumor suppressors." (PMID 36900315, 2023). "Compared with normal tissues, IGFBP7, LBH and TFPI are low expressed in tumor tissues (P < 0.05), while KRT18, UBE2C and UBE2S were highly expressed in tumor tissues (P < 0.05)." (PMID 38077434, 2023). "Blood lakes were found in most EWS tumor samples, and these tumor cells expressed CD44, TFPI-1 and EphA2." (PMID 35354905, 2022). "TF, TFPI-1 and TFPI-2 are overexpressed by tumour cells, and experimental evidence highlights their role in VM." (PMID 36224457, 2022).
tumor (continued). "It is worth emphasizing that TFPI has the ability to inhibit vascular endothelial growth factor (VEGF), plasminogenesis and metalloprotease, all of which have a significant effect on tumour growth and metastasis." (PMID 29475895, 2018). "In conclusion, our study suggests that TFPI-1 is a valuable marker to predict the occurrence of DVT and tumor metastasis with a high sensitivity and specificity at the time of diagnosis of NSCLC patients." (PMID 28246607, 2017). "Our findings suggested that TFPI-1 was a valuable predictor of DVT and tumor metastasis in NSCLC patients." (PMID 28246607, 2017). "Based on this objective, we evaluated the significance of TFPI-1 for predicting DVT and tumor metastasis at the time of diagnosis of NSCLC." (PMID 28246607, 2017). "Therefore, different TFPI-1 concentration range might result from different tumor type." (PMID 28246607, 2017). "In gene expression arrays, the overexpression of TLR4 in tumor cells correlated with gene expression of ATF-3, IL-6, CDH13, CXCL-1 and TFPI." (PMID 28982115, 2017). "Heparanase also interacts with tissue factor pathway inhibitor (TFPI) on the cell surface, leading to dissociation of TFPI from the cell membrane of endothelial and tumor cells, resulting in decreased anticoagulant capacity at the cell surface." (PMID 27322195, 2016). "However, if selectins were upregulated on the endothelium (post-exposure to inflammatory cytokines or vasoactive mediators), it is possible that induction of rolling behavior in cancer cells may sufficiently slow the velocity of circulating tumor cells to promote adhesion to TFPI." (PMID 25849335, 2015). "Only two genes (MGST1 and TFPI) were differentially expressed between low and high SF2 groups in both tumour types." (PMID 24466029, 2014). "TFPI-2 is a Kunitz-type serine protease inhibitor homologous to tissue factor pathway inhibitor (TFPI), and its down-regulation in cancer has been proposed to contribute to tumour malignancy due its role in ECM remodelling." (PMID 23703216, 2013). "TFPI may influence LUAD through TF pathway, involvement in tumor progression, potential roles in drug resistance, and links to smoking-induced changes." (PMID 38576019, 2024). "Nevertheless, the role of TFPI in cancer progression and tumor growth is not as unambiguous as the first impression suggests it to be." (PMID 36900315, 2023). "In the present study, we found that there were significantly lower TFPI-1 levels in NSCLC patients either with DVT or with tumor metastasis than in those patients without DVT or tumor metastasis, respectively." (PMID 28246607, 2017). "The targets of aptamers actually in clinical trials are extracellular proteins (VEGF165, C5, PDGFβ, coagulation factor IXa, A1 domain of von Willebrand factor, thrombin, TFPI, CXCL12, CCL2, hepcidin peptide hormone), except nucleolin which is highly expressed at the surface of several tumor cells." (PMID 28635657, 2017). "Proposed chemotherapeutic mechanisms include interference with cellular proliferation, release of tissue factor pathway inhibitor (TFPI) from vascular endothelium, anti-inflammatory properties, and inhibition of heparanase activity resulting in decreased tumor invasion and metastasis." (PMID 27384570, 2016). "This direct binding of TF/FVIIa to TFPI is in agreement with our result that FXa is not required in mediating adhesion of TF-expressing tumor cells to immobilized TFPI." (PMID 25849335, 2015). "Heparanase was shown to up-regulate tissue factor (TF) expression and interact with tissue factor pathway inhibitor (TFPI) on the cell surface, leading to dissociation of TFPI from the cell membrane of endothelial and tumor cells, resulting in increased cell surface coagulation activity." (PMID 23908827, 2012).
tumor (continued). "A total of 56 molecules are annotated as affecting neoplasia and eight of these are dysregulated over 1.5 fold in Ad12-TC compared to Ad5-TC: down-regulation of ATM, CD19, CD3G, GADD45B, HPSE, TFAP2A and TFPI was observed, whereas levels of EGFR were found to be up-regulated." (PMID 19200380, 2009). "However, unlike other Kunitz-type inhibitors, such as TFPI and TFPI-2, Amblyomin-X showed tumor cell specificity." (PMID 36052162, 2022). "Interestingly, peptides from TFPI-2 that inhibited the procoagulant activity of heparanase, but not the catalytic activity, also reduced tumor growth and vascularisation in murine tumor models." (PMID 31850210, 2019). "There is growing evidence for non-hemostatic tumor-suppressive activities of TFPI." (PMID 25882602, 2015). "TFPI, as the precursor mRNA of hsa_circ_0057335, has been proved to be closely related to the increased expression of CD33 in CHOL and the decreased expression of TFPI‐2 may inhibit cell migration and tumor invasion, playing an essential role in the carcinogenesis and progression of CHOL." (PMID 40304434, 2025). "Total TFPI (α + β) mRNA expression was increased in patients with PR-negative tumors (P = 0.021), and in patients with HER2-positive tumors, larger tumor sizes, and positive lymph nodes, although power was lacking to achieve statistical significance." (PMID 25882602, 2015). "Unlike ECs, VM-lining tumor cells express NRP1, VEGF-C, TIE-1, endoglin, tissue factor pathway inhibitor (TFPI1), laminin subunit γ2 (LAMC2), and EphA2, whereas they do not express VEGF receptors -1 and -2, TIE-2, CD31, vascular adhesion protein-1 (VCAM-1) and P-selectin." (PMID 30717262, 2019).